CPT1A (carnitine palmitoyltransferase 1A)
Diseases named in the same sentence as CPT1A in open-access papers (continued):
Sharing a sentence is not in itself a finding about the gene and the disease.
ovarian carcinoma (continued). "We detected the protein expression of CPT1A and MFF in ovarian cancer cell lines and found that CPT1A and MFF were indeed positively correlated at the protein level." (PMID 37291333, 2023). "Altogether, these results suggest that CPT1A promotes ovarian cancer cell proliferation by inhibiting Parkin-mediated ubiquitin-proteasome degradation of MFF." (PMID 37291333, 2023). "It has been reported that the key enzyme of FAO is abnormally expressed in malignant tumors, especially in ovarian cancer, and the abnormally high expression of CPT1A is closely related to the poor prognosis of ovarian cancer patients." (PMID 37199651, 2023). "Our previous study showed that CPT1A is highly expressed in ovarian cancer tissue cells and promotes the occurrence and development of ovarian cancer." (PMID 37291333, 2023). "Our findings reveal new role and molecular mechanisms by which CPT1A regulates mitochondrial dynamics to promote ovarian cancer progression through modulation of MFF succinylation." (PMID 37291333, 2023). "Abnormal CPT1A expression was associated with the poor OS of AML, ovarian cancer, and glioblastoma stem cells." (PMID 35359394, 2022). "Mechanistically, miR-33b directly targets TAK1, thereby decreasing the expression of FASN and CPT1A in ovarian cancer cells, which reduces OCM-promoted fatty acid synthesis and ATP production." (PMID 34638280, 2021). "Mechanistic studies emphasized that miR-33b directly targets TAK1, which leads to downregulation of FASN and CPT1A, explaining the inhibitory effects of miR-33b on the lipid metabolic activities of ovarian cancer cells." (PMID 34638280, 2021). "Restoration of miR-33b negatively regulated the TAK1/fatty acid synthase (FASN)/carnitine palmitoyltransferase 1A (CPT1A)/NF-κB signaling axis, leading to suppression of peritoneal metastases of ovarian cancer." (PMID 34638280, 2021). "Studies on ovarian cancer have suggested that crucial enzymes that mediate metabolic reprogramming, such as FASN and CPT1A, are overexpressed in tumor tissues, which is associated with poor prognosis and survival rates." (PMID 34638280, 2021). "In summary, miR-33b acts as a tumor suppressor, inhibiting oncogenesis and targeting ovarian cancer lipid metabolism by downregulating TAK1/FASN/CPT1A/NF-κB signaling." (PMID 34638280, 2021). "Up to this point, we seem to be able to explain, to a certain extent, why CPT1A acts as a tumor suppressor gene in renal clear cell carcinoma, instead of acting as an oncogene in ovarian cancer, leukemia, and colorectal cancer." (PMID 33381539, 2020). "Knockdown of CPT1A expression reduced the cellular level of ATP and induced the cell cycle arrest at G0/G1 in ovarian cancer cells, indicating that the CPT1A-mediated β-oxidation controlled the proliferation through regulating cell cycle process." (PMID 33194756, 2020). "In contrast, Etomoxir, a specific inhibitor of CPT1A, can inhibit the proliferation of ovarian cancer cells." (PMID 33194756, 2020). "Genetic or pharmacological inhibition of CPT1A exerts anti-tumor activity in prostate cancer, melanoma, breast, and ovarian cancer." (PMID 29907133, 2018). "In the present study, we demonstrated that CPT1A was highly expressed in most ovarian cancer cell lines and primary ovarian serous carcinomas." (PMID 26716645, 2016). "CPT1A knockdown inhibited proliferation of ovarian cancer cells not only in monolayer culture but also in soft agar." (PMID 26716645, 2016). "Recent reports have identified CPT1A as supporting tumor growth and survival in several cancer types including that of leukemia and lymphoma, prostate cancer and ovarian cancer." (PMID 27563814, 2016). "Inactivation of CPT1A decreased cellular ATP levels and induced cell cycle arrest at G0/G1, suggesting that ovarian cancer cells depend on or are addicted to CPT1A-mediated FAO for cell cycle progression." (PMID 26716645, 2016).
ovarian carcinoma (continued). "Based on the analysis of pre-existing expression and patient outcome data, we found that CPT1A overexpression contributed to poor survival of ovarian cancer." (PMID 26716645, 2016). "We analyzed CPT1A protein expression in 18 high-grade ovarian serous carcinomas (Stage II–IV), the most common type of epithelial ovarian cancer, by immunohistochemical (IHC) staining." (PMID 26716645, 2016). "ShRNA knockdown of CPT1A or treatment with etomoxir for 24 hours induced significant increases in G0/G1 population with concomitant decreases in S and G2/M phases in all ovarian cancer cell lines examined." (PMID 26716645, 2016). "Knockdown of CPT1A expression also suppressed tumorigenicity and aggressiveness of ovarian cancer cells in SCID mice." (PMID 26716645, 2016). "Ovarian cancer cells rely on or are “addicted” to CPT1A activity for maintaining growth and the malignant phenotype." (PMID 26716645, 2016). "Our results indicated that CPT1A is highly expressed in most ovarian cancer cell lines and ovarian serous carcinomas." (PMID 26716645, 2016). "The CPT1A-dependent FAO functions to restrain the FoxO transcriptional activity in ovarian cancer cells." (PMID 26716645, 2016). "Immunoblotting analysis indicated that most ovarian cancer cell lines expressed high levels of CPT1A." (PMID 26716645, 2016). "P21 was strongly induced by CPT1A-sh knockdown or etomoxir across ovarian cancer cell lines examined." (PMID 26716645, 2016). "Additionally, carnitine palmitoyltransferase 1A (CPT1A), which is a rate-limiting enzyme of fatty acid β-oxidation, was upregulated in ovarian cancer cells." (PMID 40564899, 2025). "Ovarian cancer cells elevate the expression of CPT1A to maintain a high FAO level." (PMID 40709184, 2025). "In particular, CPT1A has found to be overexpressed in most ovarian cancer cell lines and primary ovarian serous carcinomas, to correlate with poor overall survival of ovarian cancer patients, and to be upregulated in cells cultured in suspension namely mimicking in vitro anoikis resistance." (PMID 38491077, 2024). "Ovarian cancer cell lines were proven to be dependent on CPT1A mediated fatty acid oxidation for cell cycle progression since the inactivation of CPT1A decreased ATP levels and induced cell cycle arrest at G0/G1, moreover CPT1A deficiency also suppressed anchorage-independent growth." (PMID 38491077, 2024). "Furthermore, the effects of amiodarone on the lipid metabolism of epithelial ovarian cancer cells were evaluated to better explore its potential as an inhibitor of CPT1A, confirming its activity." (PMID 38491077, 2024). "Therefore, CPT1A is a desirable target for the treatment of paclitaxel resistance in ovarian cancer." (PMID 38003694, 2023). "Over-expression of CPT1A correlates strongly with poor patient outcomes of ovarian cancer." (PMID 38003694, 2023). "This suggests that the mitochondrial fusion and fission morphology is closely related to ovarian cancer cell growth and proliferation, and that CPT1A might promote cell growth and proliferation by regulating mitochondrial dynamics." (PMID 37291333, 2023). "Moreover, CPT1A is overexpressed in most ovarian cancer cell lines, primary ovarian serous carcinomas, and a subset of high-grade serous ovarian cancers (HGSOCs)." (PMID 37601653, 2023). "Lipid-rich microenvironment may cause epigenetic silencing miR-33b, which negatively modulates ovarian cancer peritoneal metastases by suppressing TAK1/FASN/CPT1A/NF-κB signaling." (PMID 38003694, 2023). "However, the inactivation of CPT1A induced cell cycle arrest at G0/G1, suggesting that ovarian cancer cells depend on or are addicted to CPT1A-mediated FAO for cell cycle progression." (PMID 37686221, 2023). "The downregulation of CPT‐1A in ovarian cancer cells was found to decrease FAO and ATP production." (PMID 35243817, 2022).
ovarian carcinoma (continued). "Importantly, FASN or CPT1A suppression results in a reduction in NF-κB activities and, as a consequence, affects the proliferation, migration, and invasion of ovarian cancer cells." (PMID 34638280, 2021). "Given that fatty acid synthesis and oxidation can negatively regulate each other, this poses an intriguing question as to how the ovarian cancer cells are able to overcome the regulatory effects of malonyl CoA, a substrate for fatty acid synthesis and an allosteric inhibitor of CPT1A." (PMID 32312965, 2020). "However, CPT1A in ovarian cancer, leukemia, and colorectal cancer primarily promotes the occurrence and development of tumors by promoting FAO, which can result in a large amount of ATP." (PMID 33381539, 2020). "This may be due to the fact that ovarian cancer cells rely on CPT1A-mediated FAO to maintain growth and malignant phenotypes." (PMID 33381539, 2020). "In addition to this evidence, a recent study reports that inhibition of liver form-CPT-1A activity suppresses cell proliferation and induces cell cycle arrest in ovarian cancer cells." (PMID 29546056, 2018). "Overexpression of CPT1A correlated with a poor overall survival of ovarian cancer patients." (PMID 26716645, 2016). "CPT1A facilitates succinylation at the K302 site to impede Parkin-mediated degradation of mitochondrial fission factor, regulating mitochondrial dynamics and activating sterol regulatory element-binding protein 1 to promote lipid desaturation in ovarian cancer 51, 52]." (PMID 41219902, 2025). "CPT1A upregulation has been found to promote the proliferation, survival, and invasion of several cancer types, including colorectal cancer, nasopharyngeal cancer, ovarian cancer, glioblastoma, gastric cancer, and HCC, and in many cases is associated with poor prognosis and metastasis." (PMID 37601653, 2023). "To test whether the LSTase activity of CPT1A that stabilizes MFF may contribute to cell proliferation in ovarian cancer cells, we exogenously overexpressed H473A in the background of CPT1A knockdown and found that CPT1A WT rescued mitochondrial fission and cellular ATP production, but H473A did not." (PMID 37291333, 2023). "In HGSOC, CPT1A is directly targeted by upstream TAK1 and indirectly targeted by miR-33b, and is able to promote peritoneal metastasis and dissemination of ovarian cancer cells by affecting the activation of NF-κB signaling." (PMID 39596847, 2024). "Together, these results further demonstrate that CPT1A regulates mitochondrial dynamics by regulating MFF expression, which in turn promotes mitochondrial function and cell growth in ovarian cancer cells." (PMID 37291333, 2023). "Our study futher shows that CPT1A regulates mitochondrial fission and function through mitochondrial fission factor (MFF) to promote the growth and proliferation of ovarian cancer cells." (PMID 37291333, 2023). "A tissue array with 100 paraffin-embedded samples, including 80 ovarian cancer tissues, 10 paracancerous tissues, and 10 normal ovarian tissues, were stained with MFF or CPT1A antibody by immunohistochemistry (IHC)." (PMID 37291333, 2023). "We also showed that cisplatin induces the expression of HSP27 and FAO markers (i.e., CPT1A, CD36) in cisplatin-resistant ovarian cancer cells through ROS-dependent mechanisms as NAC treatment attenuates cisplatin induction of HSP27 and FAO." (PMID 37628819, 2023). "Overall survival analysis was performed to investigate the prognostic effects of CPT1A and ATP1B1 in ovarian cancer." (PMID 38003694, 2023). "Similar to the ovarian cancer cell line results, the expression of MFF and CPT1A showed a high positive correlation." (PMID 37291333, 2023). "Intriguingly, TAK1−/− ovarian cancer cells exhibited a marked reduction in FASN and CPT1A expression after OCM maintenance." (PMID 34638280, 2021).
ovarian carcinoma (continued). "Our present study observed that depletion of TAK1 leads to decreased FASN and CPT1A expression, and consequently, this inhibition of lipid metabolic activities results in suppression of NF-κB activation in OCM cocultured ovarian cancer cells." (PMID 34638280, 2021). "Another study showed that the expression of carnitine palmitoyltransferase 1A (CPT1A), the rate-limiting enzyme of fatty acid β-oxidation (FAO), is increased in ovarian cancer tissues correlating with a poor overall survival of cancer patients." (PMID 32629884, 2020). "Our results indicated that CPT1A, the rate-setting enzyme of FAO is abundantly expressed in a high percentage of ovarian serous carcinomas and ovarian cancer cell lines." (PMID 26716645, 2016). "In the present study, we examined expression and biological significance of CPT1A, the most widely distributed and enzymatically active form of the CPT1 family, in human ovarian cancer that replicates and spreads within the fat-rich abdomen." (PMID 26716645, 2016). "In ovarian cancer, CPT1A promoted the succinylation of mitochondrial fission factor (MFF) at K302 to regulate mitochondrial fission and function and promoted the growth and proliferation of ovarian cancer cells." (PMID 39781339, 2025). "Additionally, CPT1A promotes the succinylation of MFF at the K302 site, which helps prevent Parkin‐mediated ubiquitin–proteasome degradation and significantly inhibits ovarian cancer progression." (PMID 40070041, 2025). "Carnitine palmitoyltransferase 1A (CPT1A) is characterized by regulating mitochondrial fission and function through the mitochondrial fission factor (MFF) succinylation mechanism to promote the proliferation of ovarian cancer cells." (PMID 38711526, 2024). "Even though over-expression of both CPT1A and ATP1B1 enhances the paclitaxel resistance of ovarian cancer cells, a higher CPT1A expression level allows cancer cells the obtention of stronger metastasis ability, while a high ATP1B1 expression level inhibits metastasis." (PMID 38003694, 2023). "Here, we showed evidence that CPT1A could regulate the stability of MFF at the posttranslational modification level, thereby promoting the fission state of mitochondria in ovarian cancer." (PMID 37291333, 2023). "In this study, we found that CPT1A can promote the succinylation of MFF through its lysine succinyltransferase activity, regulate mitochondrial dynamics and promote the growth and proliferation of ovarian cancer cells." (PMID 37291333, 2023). "Interestingly, the genetic and pharmaceutical inhibition of HSP27 upregulated carnitine palmitoyltransferase I alpha (CPT1A), the rate-limiting enzyme of FAO, to sustain ovarian cancer cell survival during cisplatin treatment." (PMID 37628819, 2023). "We next investigated whether depletion of TAK1 suppresses fatty acid biosynthesis and ATP production in OCM-cocultured ovarian cancer cells by targeting FASN and CPT1A." (PMID 34638280, 2021). "We observed a dramatic decrease in CPT1A expression and FAO rate in FASN-knockdown ES2 cells, suggesting that fatty acid synthesis might be an upstream regulator of FAO in ovarian cancer cells." (PMID 32312965, 2020). "High expression levels of CPT1A predict unfavorable clinical outcomes in AML and ovarian cancer." (PMID 29907133, 2018). "In contrast to our observation of ATP downregulation and AMPK activation in ovarian cancer cell lines, these authors did not observe ATP depletion in CPT1A-inactivated endothelial cells, suggesting complex roles of CPT1A and FAO in different cell types." (PMID 26716645, 2016). "In the present study, however, we observed abundant expression of CPT1A, but not other CPT1A isoforms in ovarian cancer cells." (PMID 26716645, 2016). "Upregulation of p21 seems to be a major effector of CPT1A depletion although we can't rule out the possibility for involvement of additional unrecognized players in cell cycle arrest of ovarian cancer cells." (PMID 26716645, 2016).
ovarian carcinoma (continued). "The cell lines expressing most abundant CPT1A protein such as SKOV-3, Caov-3, OVCA-432 and OVCAR-3 also showed highest levels of CPT1A mRNA, suggesting that a transcriptional mechanism mediates CPT1A overexpression in ovarian cancer cells." (PMID 26716645, 2016). "Together with the results that CPT1A affects DRP1 recruitment to mitochondria, we hypothesize that Drp1 recruitment to mitochondria is closely related to the presence of total MFF in ovarian cancer cells and that CPT1A regulates mitochondrial dynamics by regulating MFF expression." (PMID 37291333, 2023). "CPT1A, SCD and FASN may form an adjustable lipid metabolism enhancing pathway with CPT1A as the center, which plays a key synergistic role in the development of paclitaxel resistance in ovarian cancer." (PMID 38003694, 2023). "Here, we identified that OCM remarkably enhanced FASN and CPT1A expression in ES-2 cells compared with coculture in 1% FBS-negative control medium, whereas the OCM-mediated upregulation of FASN and CPT1A was attenuated upon overexpression of miR-33b in ovarian cancer cells." (PMID 34638280, 2021). "Thus, our data suggest that a lipid-rich microenvironment may cause epigenetic silencing of miR-33b, which negatively modulates ovarian cancer peritoneal metastases, at least in part, by suppressing TAK1/FASN/CPT1A/NF-κB signaling." (PMID 34638280, 2021). "In addition, it was found that CPT1A can act in the succinylation of the lysine 302 (K302) locus of the downstream target gene MFF, inhibit its ubiquitin-proteasome degradation, and play a role in promoting cancer by affecting its expression level in ovarian cancer cells." (PMID 39596847, 2024). "The expression of CPT1A-G710E did not restore cellular ATP but significantly rescued the growth and proliferation of ovarian cancer cells, suggesting that the decrease in cellular ATP by CPT1A knockdown may not be the only mechanism for the inhibition of cell growth and proliferation." (PMID 37291333, 2023).